MYF5 (myogenic factor 5)
Diseases named in the same sentence as MYF5 in open-access papers (continued):
Sharing a sentence is not in itself a finding about the gene and the disease.
tumor (27 papers, 1991 to 2025). "Our finding of a striking difference in DNA methylation patterns between mouse RMS tumours in which driver mutations were directed to the Myf5 or Pax7 lineage is consistent with the dynamic events that occur during myogenic development." (PMID 39812007, 2025). "Based on their genotypes, we identified n = 23 tumours corresponding to the ML cluster (Pax3::Foxo1 in Myf5, Myf6, or Pax3 lineage) and n = 33 tumours corresponding to the MR cluster (other mutations in any lineage or Pax3::Foxo1 in Pax7 lineage)." (PMID 39812007, 2025). "In concert with these findings, the DM/DE genes between Myf5 and Pax7 lineage‐related tumours are associated with muscle development‐related gene subsets." (PMID 39812007, 2025). "Analysis of mice at necropsy revealed that only 2 of 12 mice had tumors derived from MYF5-deficient Rh18 cells and that overall tumor weight was greatly reduced when compared with control Rh18 knockdown cells (p<0.01; Student’s t-test)." (PMID 28080960, 2017). "Here, we used a transgenic zebrafish model to show that Myf5 is sufficient to confer tumor-propagating potential to RMS cells and caused tumors to initiate earlier and have higher penetrance." (PMID 28080960, 2017). "SELP+ HEVs and APOD+ myCAFs foster favorable immunomodulatory stromal niches for improved outcomes, while STMN1+ cECs and MYF5+ MSCs form immunosuppressive niches in tumor invasion regions, highlighting therapeutic targets." (PMID 40107247, 2025). "As only one tumour arose in the setting of Pax3::Foxo1 directed to the Myf5 lineage, which is often embryonic lethal, the usual impact of Pax3::Foxo1 on DNA methylation in this lineage is unclear." (PMID 39812007, 2025). "In particular, we compared differential expression between four Myf5 lineage tumours and 10 Pax7 lineage tumours using available gene expression data." (PMID 39812007, 2025). "Conversely, the second niche, identified primarily in patients who did not respond to mono-immunotherapy, is distinguished by the proliferation of STMN1+ cECs and a significant accumulation of MYF5+ MSCs at the invasive frontiers of the tumor." (PMID 40107247, 2025). "These dual roles in promoting tumor advancement and immune evasion suggest that MYF5+ MSCs represent an underexplored stromal subset driving immunotherapy resistance, highlighting their potential as a therapeutic target warranting further investigation." (PMID 40107247, 2025). "Two distinct methylation‐defined subsets were found for GEMM RMS tumours with no/low Pax3::Foxo1 expression: one subset enriched in Pax7 lineage tumours and a second subset enriched in myogenic factor 5 (Myf5) lineage tumours." (PMID 39812007, 2025). "Of note, most of these DM/DE genes were hypomethylated and overexpressed in the MR1/Myf5 compared to the MR2/Pax7 tumours." (PMID 39812007, 2025). "In contrast, tumours with the Myf5 lineage were exclusively enriched in the MR1 subset (4/8, 50%) and were absent in the MR2 subset (0/12, 0%) (p = 0.014)." (PMID 39812007, 2025). "In transgenic FN-RMS zebrafish models, myog+ tumor cells are less proliferative than myf5+ cells, but are able to cross zebrafish myotomes, demonstrating a more migratory phenotype." (PMID 39902277, 2024). "In both Myf5–Cre/hSS1 and Myf5–Cre/hSS2 lineages, tumor onset, equal between genders, was mainly within skeletal muscle due to Myf5-specific expression in skeletal muscle-committed cells." (PMID 36765545, 2023). "With this approach, tumor subpopulation and heterogeneity were labeled based on the activation of different promoters (myf5, myogenin-H2B, and mylpfa) at different stages in the muscle development." (PMID 37958442, 2023). "MYC bound to the promoter containing the consensus MYC binding motif (CACGTG) of YBX1, CD133 and muscle satellite/RMS tumor propagating cell markers MYF5 and PAX7." (PMID 37345125, 2023).
tumor (continued). "This fact was evidenced by the considerable reduction in tumour development following the elimination of BA-tilted cells that were positive for UCP1 or Myogenic Factor 5 (MYF5)." (PMID 37886942, 2023). "In this study, a selective enrichment of BAT-selective genes was observed in the tumor as well as the host cells, and a depletion of UCP1 and the Myf5-positive population resulted in a significantly reduced tumor size." (PMID 34831253, 2021). "Previously, we showed that SNAIL is a key regulator of ARMS tumor growth and differentiation through functional repression of MYF5 and MYOD." (PMID 32664538, 2020). "Here, rag:kRASG12D was co-injected with mylpfa:myf5 into one-cell-stage zebrafish and analyzed for tumor onset." (PMID 28080960, 2017). "One notable exception was myf5, which was also highly expressed in the G+R+ population of mylpfa:myf5 transgenic tumor as expected." (PMID 28080960, 2017). "Consistent with our histological evaluation, flow cytometric analysis revealed that differentiated, mylpfa:mCherry-positive (R+) tumor cells were greatly expanded in ERMS that aberrantly express myf5 (p=0.006, Student’s t-test)." (PMID 28080960, 2017). "Our experiments have shown that Myf5 can impart tumor-propagating potential to ERMS cells in the zebrafish model, suggesting important roles for myogenic regulatory transcription factors in regulating growth." (PMID 28080960, 2017). "Serial bioluminescence imaging showed that tumor volume was reduced in MYF5 knockdown cells while control cells continued to grow (p<0.05, Student’s t-test)." (PMID 28080960, 2017). "Taken together, these data show that re-expression of myf5 can lead to acquisition of tumor propagating potential in differentiated mylpfa-expressing ERMS cells in the zebrafish model." (PMID 28080960, 2017). "Taken together, these data show that MYF5 is required for efficient xenograft tumor cell growth in vivo." (PMID 28080960, 2017). "Future studies will address the salivary cell subtypes belonging to the Pax7, Myf5, and Myf6 lineages, timing of tumor initiation, and the potential stem-cell like plasticity of this ontogeny." (PMID 25883905, 2015). "Only after the niche was established by colonizing myogenin-positive cells did the self-renewing myf5-positive cells migrate into the newly forming tumor, ultimately driving tumor expansion and progression." (PMID 24973745, 2014). "A 2.0 kb myf3 transcript was observed in 85% of tumours, a 1.8 kb myf4 transcript was detected in 70% of tumours and a 1.7 kb myf5 transcript was observed in 55% of tumours." (PMID 1764365, 1991). "Initial examination of these clusters/subsets revealed that all GEMM tumours in ML clusters corresponded to Pax3::Foxo1 in one of three lineages (Myf5, Myf6, and Pax3) while all tumours in MR1 corresponded to DNA alterations other than Pax3::Foxo1 in these same three lineages." (PMID 39812007, 2025). "Our analysis yielded a total of 153 DM/DE genes between Myf5 lineage and Pax7 lineage tumours." (PMID 39812007, 2025). "In contrast, our previous analysis of Myf5 and Pax7 expression in these tumours indicated that the expression status of these myogenic markers did not reflect the cell of origin; this finding suggests that expression phenotype is not fully synonymous with cellular origin." (PMID 39812007, 2025). "The tumor-derived subpopulation that is high in expression of Myf5, a myogenic transcription factor that is induced in activated tissue-resident stem cells and high in proliferating myoblasts, was enriched in cells with tumor-propagating activity." (PMID 41248180, 2025). "Transgenic expression of mylpfa:myf5, a transgene that drives myf5 expression in terminally differentiated, myosin light chain 11 (mylpfa) expressing cells, resulted in higher penetrance of rag2-kRASG12D tumor formation." (PMID 39902277, 2024). "MYCi361-treated tumor cells also showed decreased expression of the stem genes pax7 and myf5." (PMID 37345125, 2023).
tumor (continued). "Collectively, our data suggest that MYOD and MYF5 likely exert import roles in regulating muscle cell identity and cell cycle regulation, both of which are required for sustained tumor growth and likely shared with normal muscle to regulate stem cell self-renewal." (PMID 28080960, 2017). "It has been suggested that miR-202-3p is an inhibitor of proliferation and may function as a tumor suppressor by targeting Gli1 which mediates Myf5 expression during somitogenesis." (PMID 25630602, 2015). "Increased migration of myog+ cells, compared to the stationary Myf5+ cells, resulted in segregation of the two cell populations, a phenomenon reproduced in human FN-RMS tumor samples." (PMID 39902277, 2024). "The myogenic factors myod and myf5 were however not significantly altered in our transcriptome analysis, possibly due to the analysis being performed on whole embryos rather than muscle tissue, but would unlikely be the only cause of delayed tumour progression in the pax3a−/−;pax3b−/− mutants." (PMID 36229514, 2022). "In total, our data show that MYF5 and MYOD are individually expressed in different RMS tumor cells and yet have similar roles in regulating cell cycle progression and proliferation in RMS." (PMID 28080960, 2017). "Here we show that Myf5 is not only a marker of TPCs in the zebrafish ERMS model, but was sufficient to impart tumor propagating potential to differentiated ERMS cells in vivo." (PMID 28080960, 2017). "To explore the role of MRFs in human RMS, we next assessed MYF5 and MYOD transcript expression in human primary tumor samples." (PMID 28080960, 2017). "Analysis of human RMS revealed that MYF5 and MYOD are mutually-exclusively expressed and each is required for sustained tumor growth." (PMID 28080960, 2017). "Our data suggest that either MYOD or MYF5 are uniquely expressed within human RMS and are each individually sufficient to drive tumor growth." (PMID 28080960, 2017). "Given the prominent role MYF5 had in regulating cell growth in human ERMS cells in vitro and imparting tumor propagating potential to differentiated zebrafish ERMS cells, we next wanted to assess if MYF5 was required for ERMS maintenance and growth in vivo." (PMID 28080960, 2017). "Higher magnification imaging of areas enriched with differentiated ERMS cells revealed the presence of myf5-GFP+ TPCs, albeit at reduced numbers when compared with other regions of the tumour (× 400 magnification)." (PMID 26790525, 2016). "A combined analysis of scRNA-seq and spatial transcriptomics revealed an abundance of STMN1+ cECs and MYF5+ MSCs at the tumor invasion front in mono-immunotherapy non-responders." (PMID 40107247, 2025). "Based on the prevalence of Myf5 and Pax7 lineages in MR1 and MR2, respectively, we examined whether the Myf5 and Pax7 genes were DM between MR1 and MR2 tumours." (PMID 39812007, 2025). "Transgenic zebrafish expressing myogenic factor 5 (myf5)-GFP, myogenin-H2B-mRFP, and mylpfa-lyn-Cyan were able to show the sub-population of developed ERMS tumors, indicating GFP fluorescence for tumor propagating cells (TPCs) and cyan fluorescence for differentiated cells." (PMID 37958442, 2023). "Myf5–Cre/SS18-SSX2 elements were viable near cartilages, and the microenvironment near cartilages appeared to prevent apoptosis of Myf5–Cre/SS18-SSX2 cells, therefore predicting tumor onset near joints." (PMID 36765545, 2023). "For example, cell transplantation and direct live cell imaging has revealed that myf5:GFP+/myosin-negative progenitor cells drive tumor growth and specifically label TPCs in this animal model." (PMID 28080960, 2017). "Using these approaches, we have been able to dynamically visualize tumour cell heterogeneity in vivo, identifying the existence of a molecularly defined tumour-propagating cell (TPC) that expresses myf5-GFP and other differentiated cell types that express myogenin and drive invasion." (PMID 26790525, 2016).
tumor (continued). "When myf5-GFP:mylpfa-mCherry double positive transgenic ERMS tumors were transplanted to the immune compromised recipients intraperitoneally, different cell types as well as tumor propagating cells were observed, which showed similar histological features to the donor zebrafish ERMS." (PMID 37958442, 2023). "Additionally, ERMS cells positive for MYF5 do not display pro-invasive capabilities, but they play supportive roles in tumor progression." (PMID 29844345, 2018). "Finally, we show that MYF5 and MYOD are also required for efficient human RMS tumor growth in vivo." (PMID 28080960, 2017). "Moreover, MYF5 and MYOD are commonly re-expressed in experimental animal models of RMS irrespective of the cell of origin suggesting roles for these transcription factors in driving tumor growth and TPC function." (PMID 28080960, 2017).
cancer (7 papers, 2012 to 2025). A tumor composed of atypical neoplastic, often pleomorphic cells that invade other tissues. "Consistent with its oncogene function, TAZ S89A induced expression of the ERMS cancer stem cell gene Myf5 and the serine biosynthesis pathway (Phgdh, Psat1, Psph) in C2C12 myoblasts." (PMID 27184927, 2016). "Our experiments uncovered that differentiated ERMS cells seed new areas of growth, followed later by slow-moving, less-differentiated myf5+ TPCs, challenging the notion that cancer stem cells drive invasion and metastasis." (PMID 26790525, 2016). "TAZ S89A drove increased expression of the cancer‐related genes Phgdh, Psat1, Psph and Myf5, although Ctgf mRNA levels were unchanged." (PMID 27184927, 2016). "Notably, STMN1+ cECs and MYF5+ MSCs were found to be spatially closer to cancer cells than to other cell types, particularly in Pt27 and Pt59, who exhibited progressive disease." (PMID 40107247, 2025). "Together this suggests that YAP and TAZ may contribute to the maintenance of a cancer stem cell population in ERMS through the expression of Myf5." (PMID 27184927, 2016). "However, the role of MYF5+ MSCs within the TME of immunotherapy-resistant cancers remains unclear." (PMID 40107247, 2025). "Importantly, transcription factors have recently been therapeutically targeted, raising hope that developing drugs that inhibit MYF5 and MYOD cancer cell dependencies could be efficacious in treating RMS patients in the future." (PMID 28080960, 2017).
infection (3 papers, 2004 to 2025). The state of being infected such as from the introduction of a foreign agent such as serum, vaccine, antigenic substance or organism. "The expression of Myogenic Regulatory Factors Myf5, MyoD, Mrf4 and myogenin was modulated by the infection." (PMID 31828046, 2019). "Also upregulated are PAX7, MYOG, and MYF5, all classic markers of myogenic differentiation and regeneration, indicating either inappropriate activation of muscle-lineage genes or potential cellular stress responses induced by prolonged infection." (PMID 40863220, 2025). "Infection of Pax7 −/− CD45+:Sca1+ cells with Pax7 retrovirus resulted in high levels of retroviral Pax7 transcript but no expression of Myf5 mRNA by Northern blot hybridization or RT-PCR (data not shown)." (PMID 15138500, 2004).
Myopathies (2 papers, 2019 to 2024). "Additionally, we show that while Myf5-dependent depletion of all FXR1P isoforms is neonatal lethal, mice carrying mutations in exon-15 display non-lethal myopathies which vary in severity depending on the specific effect of each mutation on the protein." (PMID 30770808, 2019).
MYF5 also shares sentences with these, for which no sentence is quoted: sarcopenia (4 papers); Duchenne muscular dystrophy (3); ptosis (2); alveolar rhabdomyosarcoma (1); aortic aneurysm (1); Arrhythmia (1); breast carcinoma (1); Cachexia (1); colon cancer (1); degenerative diseases (1); dystroglycanopathy muscular dystrophy (1); embryonal carcinoma (1); epithelioid sarcoma (1); hypogonadism (1); Insulin resistance (1); malignant rhabdoid tumors (1); metabolic disease (1); neuroblastoma (1); prostate carcinoma (1); sarcoma (1); skeletal muscle disorder (1); Torticollis (1); vitamin D deficiency (1).